OSCAR (osteoclast associated Ig-like receptor)
Description:
Regulator of osteoclastogenesis which plays an important bone-specific function in osteoclast differentiation.
Synonyms: PIgR-3; PIgR3
Tractability: Antibody: UniProt places it where antibodies can reach, with high confidence; its Gene Ontology location is reachable by antibodies, with high confidence; UniProt predicts a signal peptide or a membrane-spanning region; the Human Protein Atlas places it where antibodies can reach.
Gene: Protein-coding gene on chromosome 19 (54,094,668 to 54,102,692, reverse strand). Ensembl gene ENSG00000170909.
Subcellular location: Secreted (Isoform 1); Cell membrane (Isoform 2)
Subcellular location (Human Protein Atlas): Cytosol; Nucleoplasm; Plasma membrane
Pathways (Reactome):
Immune System: Immunoregulatory interactions between a Lymphoid and a non-Lymphoid cell; Neutrophil degranulation
Gene Ontology:
Molecular function: collagen receptor activity
Biological process: osteoclast differentiation; signal transduction; collagen-activated signaling pathway
Cellular component: extracellular exosome; extracellular region; plasma membrane; specific granule lumen; tertiary granule lumen
Genetic constraint (gnomAD): Loss-of-function variants: 25 observed, 24.5 expected, observed/expected ratio (o/e) 1.02, 90% interval 0.74 to 1.42. The upper end of that interval is the gene's LOEUF score, 1.42, which puts it in group 5 of 6, group 1 being the genes least tolerant of losing a copy. Missense variants: 354 observed, 315.37 expected, observed/expected ratio (o/e) 1.12, 90% interval 1.03 to 1.23. Synonymous variants: 158 observed, 135.76 expected, observed/expected ratio (o/e) 1.16, 90% interval 1.02 to 1.33.
Homologues: Orthologues: chimpanzee OSCAR (84% identical), macaque OSCAR (82% identical), pig OSCAR (80% identical), dog OSCAR (75% identical), mouse Oscar (75% identical), rabbit OSCAR (72% identical), rat Oscar (68% identical), tropical clawed frog xilr1 (22% identical). Paralogues in human: IGSF1 (43% identical), LILRA4 (35% identical), LILRA1 (33% identical), LILRA6 (33% identical), LILRB3 (33% identical), TARM1 (33% identical), LILRA2 (32% identical), LILRA5 (32% identical), KIR3DL1 (32% identical), GP6 (32% identical), LILRB5 (32% identical), LILRB1 (31% identical), and 13 more.
Diseases named in the same sentence as OSCAR in open-access papers:
OSCAR is named in the same sentence as 44 diseases in open-access papers, as found by Europe PMC text mining. Sharing a sentence is not in itself a finding about the gene and the disease. The quoted sentences say what the papers report.
rheumatoid arthritis (4 papers, 2012 to 2024). A chronic, systemic autoimmune disorder characterized by inflammation in the synovial membranes and articular surfaces. "Increased OSCAR expression on monocytes is associated with disease activity in rheumatoid arthritis (RA) patients." (PMID 39144626, 2024). "In human rheumatoid arthritis (RA), OSCAR is induced in monocytes, facilitating their differentiation into osteoclasts and bone resorption." (PMID 32859940, 2020). "In rheumatoid arthritis (RA), OSCAR expression by monocytes is inversely correlated with disease activity." (PMID 23146195, 2012). "This study found elevated OSCAR gene expression in the blood of COPD patients in the absence of any bone disease, like rheumatoid arthritis or osteoarthritis." (PMID 39144626, 2024).
atherosclerosis (3 papers, 2017 to 2021). A disease characterized by the build-up of fatty material and calcium deposition in the arterial wall resulting in partial or complete occlusion of the arterial lumen. "The osteoclast-associated receptor (OSCAR), originally described in bone as immunological mediator and regulator of osteoclast differentiation, may be involved in cell activation and inflammation during atherosclerosis." (PMID 29226137, 2017).
melanoma (3 papers, 2020 to 2024). A malignant, usually aggressive tumor composed of atypical, neoplastic melanocytes. "Other collagen-binding receptors include osteoclast-associated immunoglobulin-like receptor (OSCAR), known to have a role in the maturation of monocyte-derived DCs, and G-protein-coupled receptor (GPR) 56, present on fibroblasts, oligodendrocytes, melanoma cells, and cytotoxic NK and T lymphocytes." (PMID 33262757, 2020). "An initial panel of markers should be done to identify the lineage of tumor: carcinoma (cytokeratin AE1/3, OSCAR, CAM5.2), lymphoma (CD20, CD3), melanoma (S-100 protein, SOX10), and sarcoma (desmin, smooth muscle actin, MDM2, ERG)." (PMID 39634259, 2024). "However, OSCAR expression was significantly lower in bladder cancer (BLCA), leukemia (different subtypes), lung cancer, and melanoma, compared with adjacent normal tissues." (PMID 34093786, 2021).
osteoporosis (3 papers, 2021 to 2025). A condition of reduced bone mass, with decreased cortical thickness and a decrease in the number and size of the trabeculae of cancellous bone (but normal chemical composition), resulting in increased fracture incidence. "Furthermore, the expression of OSCAR and its adaptor molecule, FcRγ, is upregulated in inflammatory bone disease and osteoporosis." (PMID 33912557, 2021). "Similarly, B1W significantly downregulated the mRNA expression of the osteoporosis-related genes c-Fos, TRAP, CTSK, DC-STAMP and OSCAR." (PMID 39982961, 2025).
periodontitis (3 papers, 2015 to 2024). An acute or chronic inflammatory process that affects the tissues that surround and support the teeth. "Further studies, however, are required to investigate the association of OSCAR and other ITAM-related molecules with periprosthetic bone loss and periodontitis." (PMID 33912557, 2021). "Similarly, OSCAR has been identified at sites of osteolysis in tissues with periodontitis and in mild gingivitis, where it co-localized with TRAP-positive cells." (PMID 33912557, 2021). "This study showed that treatment in the periodontitis model significantly reduced the expression of genes (COX-2, NOS-2, INF-γ, OSCAR and TGFβ)." (PMID 38918842, 2024).
prostate carcinoma (2 papers, 2024 to 2025). A carcinoma that arises from epithelial cells of the prostate gland. "These genes, AREG, CXCR4, IL11, KITLG and OSCAR, are known to play a significant role in tumour progression and metastasis promotion of prostate cancer as well as colorectal or pancreatic cancers." (PMID 39374163, 2025).
breast carcinoma (1 paper, 2021). "OSCAR mRNA levels in cancer compared to healthy tissues revealed that OSCAR expression was higher in brain and central nervous system cancers, breast cancer (BRCA), gastric cancer, head and neck cancer (HNSC), leukemia, and pancreatic adenocarcinoma (PAAD), compared with adjacent normal tissues." (PMID 34093786, 2021).
endocervical carcinoma (1 paper, 2021). A carcinoma that arises from epithelial cells of the endocervix. "Only in a small number of cancer types, such as cervical and endocervical carcinoma (CESC), KIRP, LUAD, SKCM, and uterine corpus endometrial carcinoma (UCEC), did OSCAR expression implicate a protective role, as high expression was associated with better prognosis for these cancer types." (PMID 34093786, 2021).
lung adenocarcinoma (1 paper, 2021). A carcinoma that arises from the lung and is characterized by the presence of malignant glandular epithelial cells. "Only in liver hepatocellular carcinoma (LIHC), lung adenocarcinoma (LUAD), and lung squamous cell carcinoma (LUSC), was OSCAR expression significantly lower than that in adjacent normal tissues." (PMID 34093786, 2021).
lymph node metastasis (1 paper, 2021). "Higher expression of OSCAR correlated with lymph node metastasis or advanced stage subgroups." (PMID 34093786, 2021).
rhabdomyosarcoma (1 paper, 2025). A rare aggressive malignant mesenchymal neoplasm arising from skeletal muscle. "Virtually all examples of TFCP2-rearranged rhabdomyosarcoma are diffusely positive for pancytokeratins, e.g., AE1/AE3, OSCAR, MNF116, and desmin, as well as myogenin and/or MYOD1, with MYOD1 showing higher sensitivity." (PMID 40526340, 2025).
synovitis (1 paper, 2024). Inflammation of a synovial membrane. "By the end of the third week, this induced in vivo chondrocyte-overexpression of OSCAR, damaged the glycosaminoglycans in the articular cartilage, and induced synovitis." (PMID 38310093, 2024).
tumor (6 papers, 2021 to 2026). "To further investigate correlations between OSCAR and macrophage subtypes in multiple cancer types, we focused on markers of monocytes, tumor-associated macrophages (TAMs), and M1 and M2 macrophages using TIMER." (PMID 34093786, 2021). "We further uncover OSCAR as its key functional receptor, mediating tumor progression and metabolic reprogramming through Hippo signaling modulation." (PMID 41951612, 2026). "We examined OSCAR expression correlations with lymph node metastasis and pathological stage across tumor samples using UALCAN and GEPIA2." (PMID 34093786, 2021). "High expression of OSCAR was related to low tumor purity, with increased levels of M2 macrophage polarization, T cells exhaustion, and mesenchymal phenotype in most cancer types." (PMID 34093786, 2021). "We examined OSCAR expression correlations with lymph node metastasis and stage across tumor samples using UALCAN and GEPIA2." (PMID 34093786, 2021). "Therefore, we included 20 cancers for which OSCAR expression was closely related to prognosis to investigate correlations between OSCAR expression, tumor purity, and immunocyte infiltration levels using TIMER." (PMID 34093786, 2021). "Immunohistochemically, tumor cells are positive for AE1/AE3, EMA, cytokeratin (CK), brachyury, focally S-100P, MNF116, OSCAR, and glypican 3, as per the study by Rekhi." (PMID 39233954, 2024). "Further analyzing the mechanism behind this paradox, we found strongly negative correlations between OSCAR expression and tumor purity in GBM (r=-0.648) and SKCM (r=-0.619)." (PMID 34093786, 2021). "We found negative correlations between OSCAR expression and tumor purity as well as varying directions and strengths of correlations between OSCAR and immunocyte infiltration." (PMID 34093786, 2021).
cancer (5 papers, 2021 to 2024). A tumor composed of atypical neoplastic, often pleomorphic cells that invade other tissues. "The osteoclast-associated receptor (OSCAR) is a regulator of lymphocyte differentiation and maturation, but little is known about the role of OSCAR in multiple cancer types." (PMID 34093786, 2021). "Together these findings suggest that OSCAR acted as a risk factor for prognosis in most types of cancers, and the predictive strength varied for diverse types of cancer." (PMID 34093786, 2021). "Interestingly, despite OSCAR’s stimulatory capacity, RNA expression appears to positively associate with M2 macrophage differentiation, T cell exhaustion, cancer progression and metastasis, although much remains to be learned in the context of cancer." (PMID 37662958, 2023). "OSCAR is expressed not only on osteoclasts, but also on other myeloid cell subsets, and OSCAR RNA is overexpressed in several cancers." (PMID 37662958, 2023). "Meanwhile, we found that OSCAR expression was positively correlated with multiple markers of mesenchymal phenotype in diverse types of cancer." (PMID 34093786, 2021). "We comprehensively analyzed OSCAR expression and explored its correlation with prognosis in multiple cancer types using Oncomine, TIMER, Gene GEPIA2 and CCLE." (PMID 34093786, 2021). "Vimentin is a typical marker of mesenchymal phenotype, which was positively correlated with the levels of OSCAR in 17/20 types of cancer, especially BLCA (r=0.594), COAD (r=0.759), LUSC (r=0.606), and READ (r=0.724)." (PMID 34093786, 2021). "GBM and SKCM cancer types were selected, in which their OSCAR expression levels played an opposite role in prognosis." (PMID 34093786, 2021). "We found that the genes co-expressed with OSCAR were significantly enriched in GO for myeloid leukocyte activation in these 32 types of cancers." (PMID 34093786, 2021). "In the present study, we comprehensively analyzed OSCAR expression and explored its correlation with prognosis in multiple cancer types, using Oncomine, TIMER, GEPIA2, and CCLE." (PMID 34093786, 2021). "Together these findings suggest that the strength of OSCAR activity in malignant progression and the inhibitory immune microenvironment was influenced by the infiltration of NK cells in certain types of cancer." (PMID 34093786, 2021). "OSCAR mRNA levels in cancer compared to healthy tissues revealed that OSCAR expression was higher in both GBM (p<0.05) and SKCM (p<0.05)." (PMID 34093786, 2021). "We profiled the expression of OSCAR in different types of cancer based on metastasis status using a box plot in UALCAN database." (PMID 34093786, 2021). "OSCAR expression was positively correlated with infiltrating levels of monocytes in 20/20 types of cancer, especially BLCA (CD86, r=0.718; CD115, r=0.740), CESC (CD86, r=0.756; CD115, r=0.700), THCA (CD86, r=0.836; CD115, r=0.732), and UCEC (CD86, r=0.775; CD115, r=0.727)." (PMID 34093786, 2021). "Our findings suggested that OSCAR facilitates malignancy with enhanced metastasis in multiple types of human cancers correlating to the inhibitory immune microenvironment, and which could be reversed by the infiltration of NK cells." (PMID 34093786, 2021). "OSCAR mRNA levels were upregulated in most cancer types compared with adjacent normal tissues." (PMID 34093786, 2021). "OSCAR expression also showed a strong correlation with infiltrating levels of neutrophils and dendritic cells, verified by a variety of surface markers, in the selected 20 types of cancers." (PMID 34093786, 2021). "In addition, OSCAR expression was positively correlated with infiltrating levels of TAMs in 20/20 types of cancer, especially BRCA (CCL2, r=0.428; CD68, r=0.769; IL10, r=0.542), COAD (CCL2, r=0.561; CD68, r=0.624; IL10, r=0.536), and THCA (CCL2, r=0.612; CD68, r=0.870; IL10, r=0.597)." (PMID 34093786, 2021). "We speculate that OSCAR might play an important role in the progression of cancer." (PMID 34093786, 2021).
cancer (continued). "We investigated whether OSCAR expression was correlated with prognosis in cancer patients." (PMID 34093786, 2021). "Regarding immunohistochemical staining, most sRCC stain positive for AE1/AE3, vimentin, CK OSCAR, PAX-8, and epithelial membrane antigen owing to the epithelial origin of the cancer." (PMID 39564030, 2024). "LILRB4, LAIR-1 and OSCAR are all members of a larger Leukocyte Immunoglobulin-Like Receptor (LILR) family, several members of which have been described in cancer." (PMID 37662958, 2023). "The relationship of OSCAR expression and survival rate was evaluated using the GEPIA2 database in 33 human cancers." (PMID 34093786, 2021). "Since, unlike LGR5-GFP, the OSCAR reporter does not rely on any cell type-specific promoter or activity, but instead reports low CDK9 activity it is likely to be generically useful for imaging and isolation of dormant cells in many tissue or cancer types." (PMID 34083536, 2021).
infection (2 papers, 2022 to 2024). The state of being infected such as from the introduction of a foreign agent such as serum, vaccine, antigenic substance or organism. "Since Ad-OSCAR infection of chondrocytes in vitro strongly upregulates their OSCAR expression and IA-injection of recombinant adenovirus effectively delivers genes to joint tissues, we IA-injected murine knees with Ad-OSCAR (3 weekly injections)." (PMID 38310093, 2024).
respiratory disease (1 paper, 2018). "Determination of the contribution of SP-D-mediated OSCAR signaling to respiratory and non-respiratory disease may help to clarify the reasons underlying conflicting observations of pro- and anti-inflammatory effects of SP-D." (PMID 29473039, 2018).
OSCAR also shares sentences with these, for which no sentence is quoted: osteoarthritis (3 papers); lung carcinoma (2); arteriosclerosis (1); Arthritis (1); bladder cancer (1); breast tumors (1); cardiovascular disease (1); central nervous system cancer (1); cholangiocarcinoma (1); chronic periodontitis (1); clear-cell renal cell carcinoma (1); colon adenocarcinoma (1); diabetes (1); esophageal cancer (1); gastric cancer (1); head and neck cancer (1); inflammatory bone disease (1); influenza (1); kidney chromophobe (1); leukemia (1); lung squamous cell carcinoma (1); lymphoma (1); pancreatic adenocarcinoma (1); pancreatic cancers (1); rectal adenocarcinoma (1); sarcoma (1); thyroid carcinoma (1); uterine corpus endometrial carcinoma (1).